SMAD4 (SMAD family member 4)
Diseases named in the same sentence as SMAD4 in open-access papers (continued):
Sharing a sentence is not in itself a finding about the gene and the disease.
breast carcinoma (173 papers, 2005 to 2026). "Here, we delved into the associations in between IBSP and breast cancer progression, along with the regulation of IBSP by SMAD4, which was associated with breast cancer metastasis." (PMID 39118232, 2024). "Despite the low mutation rate of SMAD4 in breast cancer, loss of SMAD4 is associated with a poor prognosis." (PMID 38914552, 2024). "Ultimately, our goal is to promote the use of SMAD4 as a predictive, diagnostic, and therapeutic molecular marker to aid in precision medicine for breast cancer." (PMID 38914552, 2024). "Of them, the association of UBR5 and SMAD4 with breast cancer prognosis was evaluated in previous studies." (PMID 36726376, 2023). "The underlying mechanism of action of FOXM1 in breast cancer involves sustained activation of SMAD3/SMAD4 activity, which further induces TGF-β-dependent EMT and promotes metastasis." (PMID 31554904, 2019). "Breast cancers with mutations in the SMAD4 gene are as sensitive to PARP inhibitors as BRCA-mutant breast or ovarian cancers." (PMID 31867281, 2019). "Loss of SIRT1 has been reported to cause hyper-acetylation of SMAD4 and promote breast cancer metastasis." (PMID 30001742, 2018). "The second observation was the strong association between SMAD4 expression and the pattern of relapse of breast cancer." (PMID 26040677, 2015). "Several independent studies indicate that deletions or intragenic mutations of the SMAD4 gene are present in more than 50% of human PDACs, but are rare in other malignancies such as lung or breast cancer." (PMID 24625091, 2014). "Smad4 mutations or deletions have been widely observed in different types of cancer, such as colorectal, pancreatic, and breast cancers; however, the detailed mechanism of Smad4 inactivation is limited." (PMID 23393589, 2013). "Future research to explore the mechanisms of deregulation of SMAD3 and SMAD4 expressions will be essential in determining their association with breast cancer risk and tumorigenesis." (PMID 21835029, 2011). "For the qPCR analysis, cDNA harboring SMAD3 and SMAD4 variants were categorized as breast cancer cases with variants (BC-VAR) and controls with variants (CO-VAR)." (PMID 21835029, 2011). "The SMAD4 variants, c.1350G > A (p.Gln450Gln) (P9) found in a patient with familial breast cancer and c.1214T > C (p.Phe362Phe) from a familial breast cancer case and a control, were predicted to result in the disruption of exonic splicing enhancers (ESE)." (PMID 21835029, 2011). "Based on these results it appears inactivating SMAD3 and SMAD4 germline mutations and splicing defects appear to occur very infrequently in breast cancer." (PMID 21835029, 2011). "Down-regulation and abnormal cellular distribution of Smad4 were associated with some ERα-positive infiltrating human breast carcinoma." (PMID 19943940, 2009). "We have demonstrated that down-regulation and relatively increased cytoplasmic localization of Smad4 were associated with some ERα-positive infiltrating human breast carcinoma." (PMID 19943940, 2009). "In conclusion, our analyses suggested that SMAD4 enhances tumor migration and invasion, and may be closely linked to tumor progression for breast cancer patients." (PMID 39118232, 2024). "Interestingly, TrkB directly associates with SMAD2, SMAD3, and SMAD4 in breast cancer tissues and cancer cell lines." (PMID 32340410, 2020). "Inactivating mutations in SMAD4 have been found in different tumor types, including breast cancers." (PMID 31487369, 2020). "SMAD4 is a common transcriptional partner for activated SMADs, the loss of which predicts liver metastasis in colon cancer and bad prognosis in patients with breast cancer." (PMID 30674353, 2019).
breast carcinoma (continued). "Mutations in CREBBP and SMAD4 have only been occasionally reported in breast cancer." (PMID 27270325, 2016). "Nevertheless, aberrant germline expressions of SMAD3 and SMAD4 may be more common in breast cancer than previously suspected and offer novel insight into their roles in predisposition and/or progression of breast cancer." (PMID 21835029, 2011). "As it has been suggested that SMAD3 and SMAD4 mutations are rare in breast cancer, we quantitatively assess whether this is the case in the germline." (PMID 21835029, 2011). "Interpreting how changes in expression of SMAD3 and SMAD4 affect their activities in the cell may distinguish their roles as a tumor suppressor or oncogene in breast cancer susceptibility." (PMID 21835029, 2011). "Smad4 mutations in breast carcinoma have also been reported." (PMID 19943940, 2009). "Association of Smad4-expression and breast cancer characteristics (n = 197)." (PMID 16438724, 2006). "However, it has been difficult to ascertain whether SMAD3 and SMAD4 mutations in breast cancer are truly rare or this understanding is due to the comparatively small sample sizes screened as noted from COSMIC." (PMID 21835029, 2011). "Thus, it is currently unknown whether germline SMAD3 and SMAD4 mutations are involved in breast cancer predisposition." (PMID 21835029, 2011). "The role of DNA methylation in the prognosis of breast cancer, particularly concerning small mothers against decapentaplegic 4 (SMAD4) and aldo-keto reductase family 1 member B1 (AKR1B1), remains largely unexplored." (PMID 41760667, 2026). "For instance, in breast cancer, miR‐224‐5p promotes tumor metastasis by targeting Smad4, but its expression is significantly downregulated in pure mucinous breast carcinoma." (PMID 39840666, 2025). "Treatment with BI sup induced SMAD4 expression to suppress cell growth in colon and breast cancer cells." (PMID 39113194, 2024). "For example, Transcriptional activity of SMAD2/SMAD3:SMAD4 heterotrimer involved in the degradation of SKI/SKIL, thus causing malignant transformation in breast cancer." (PMID 38652712, 2024). "To confirm this unexpected observation of BMP4-induced suppression of metastasis even when SMAD4 levels are low, we utilized a second model, the human triple-negative MDA-MB-468 breast cancer line that lacks SMAD4 due to a homozygous deletion." (PMID 38689334, 2024). "SIRT7 expression is decreased in breast cancer cells and correlates with poor patient prognosis, and SIRT7 can affect the invasive ability of breast cancer cells by deacetylating and degrading Smad4." (PMID 39479446, 2024). "Here, we investigate the role of SMAD4 in acquired endocrine resistance in HR + HER2− breast cancer." (PMID 38914552, 2024). "SIRT1 inhibits EMT in HMLER breast cancer cells by deacetylating Smad4 and preventing TGF-β signaling." (PMID 39479446, 2024). "In previous studies, we have reported that BMP4 potently suppresses metastasis in preclinical mouse models where breast cancer cells retained SMAD4 activity to transduce canonical signalling." (PMID 38689334, 2024). "In HR + HER2− breast cancer cells, SMAD4 has been shown to act as an ER transcriptional corepressor and to inhibit tumor growth by inducing apoptosis." (PMID 38914552, 2024). "Clinical data analysis reveals downregulated SMAD4 expression in breast cancer tissues, correlating with poor prognosis." (PMID 38914552, 2024). "To analyze another SMAD4-positive breast cancer cell line, we repeated the experiments in MDA MB 231 cells." (PMID 38731813, 2024). "In breast cancer cells, SIRT7 deacetylates SMAD4 and facilitates its degradation, which inhibits TGF-β signaling and subsequent breast cancer invasion and migration, which is possibily associated with tumor angiogenesis." (PMID 39519130, 2024). "SMAD4 has been reported to be involved in the development of glycolysis in pancreatic, colon, and breast cancers." (PMID 38686046, 2024).
breast carcinoma (continued). "Intriguingly, the effect of SIRT7-mediated deacetylation of SMAD4 appears to exert tumor-suppressive roles in breast cancer and, as illustrated later, in oral squamous tumors which sharply differ from its function in melanoma and prostate cancer." (PMID 38383727, 2024). "In breast cancer, studies have demonstrated that SMAD4 promotes the ectopic expression of UCP2, triggering the glycolytic process and thereby promoting tumor growth." (PMID 38686046, 2024). "It is hoped that our study on the mechanism of IBSP regulation by SMAD4 will create new insights and opportunities for the therapy of breast cancer." (PMID 39118232, 2024). "Genes regulated by BMP4 and/or SMAD4 were assessed in a publicly available database of gene expression profiles of breast cancer patients." (PMID 38689334, 2024). "Fascin-1 is responsible for invadopodia formation, migration and invasion of breast cancer cells, and it is a target of (TGFβ)-Smad4 signaling pathway which, in breast, has been found to be under the control of GATA-3." (PMID 37511011, 2023). "One of the most frequent regions with LOH in breast cancer is 18q, and SMAD4 and DCC located at 18q21 are inactivating tumor-suppressor gene candidates." (PMID 37650999, 2023). "In this study, methylation of SMAD4 can distinguish breast cancer patients from healthy and benign individuals, where methylation degree of SMAD4 in breast cancer is higher than methylation in benign and healthy controls." (PMID 33825073, 2021). "On the other hand, serving as the central mediator of TGF-β signaling pathway, SMAD4 is a potential prognostic marker of breast carcinoma development, and it is critical for stem cells’ self-renewal." (PMID 34803458, 2021). "As SMAD4 is directly involved in the transcription of target genes, its higher expression can be related to the invasiveness of breast cancer to other parts like lungs, bones, and axillary lymph nodes." (PMID 34297787, 2021). "These investigations about methylation status of SMAD4 in our study were the first study reporting implication of the methylated SMAD4 in Egyptian breast cancer patients." (PMID 33825073, 2021). "miRNAs (miR-29a and miR-140, miR-148a) can be an effective diagnostic and prognostic marker as they regulate SMAD4 and SMAD2 expression respectively in breast cancer blood and biopsy samples." (PMID 34297787, 2021). "Their results showed that TGF-β receptor kinase inhibitors and tumor specific Smad4 knockdown suppressed the invasion and metastasis of breast cancer in zebrafish xenograft model." (PMID 34168559, 2021). "On the other hand, high expression of SMAD4 in the MDA-MB-231 breast cancer cell line has been seen to increase the basal level of IL-11 on stimulation by TGF-β1." (PMID 34297787, 2021). "SMAD4 has also been reported to act as a tumor suppressor in the MDA-MB-468 breast cancer cell line." (PMID 34297787, 2021). "For example, FFAs treatment increases the expression of plasminogen activator inhibitor-1 and SMAD4 to promote cell invasion and metastasis in breast cancer cells." (PMID 33801246, 2021). "Loss of ppGalNAc-T4 resulted in elevated pSmad2/3 and nuclear Smad4 accumulation in breast cancer cells." (PMID 33234595, 2021). "Methylation status of PTEN and SMAD4 is a promising blood marker for early detection of breast cancer." (PMID 33825073, 2021). "Similar to our findings, a recent report demonstrated the role of SIRT7 in promoting MET in breast cancers through SMAD4 deacetylation mediated suppression of Slug and Zeb1 transcription." (PMID 32656073, 2020).
breast carcinoma (continued). "In contrast, Smad4 was also found to play important oncogenic roles in a vast diversity of cancer types, including breast cancer, ovarian cancer, glioblastoma, and HCC." (PMID 31721429, 2020). "SIRT7 was found to suppress EMT in oral squamous cells, carcinoma cells, and breast cancer cells by promoting SMAD4 deacetylation, leading to increase of E-cadherin and down regulation of N-cadherin and Vimentin." (PMID 32656073, 2020). "The results found that SIRT7 promoted the degradation of SMAD4, which is the key factor in TGF-β pathway, which indicated the potential of the therapeutic target for SMAD4-mediated breast cancer." (PMID 33193750, 2020). "In contrast, Smad4 mainly contributes to breast cancer bone metastasis formation through transcriptional activation of IL‐11, a gene implicated in bone metastasis." (PMID 33377651, 2020). "TrkB expression is significantly increased in tissues obtained from breast cancer patients relative to normal breast tissue, with TrkB strongly associating with SMAD2, SMAD3, and SMAD4." (PMID 32340410, 2020). "We showed that upon dicarbonyl stress, breast cancer cells had a significant decrease in SMAD4 and had enhanced migratory capacity." (PMID 30674353, 2019). "Our findings indicated that SENP2 plays a positive role in Smad4 desumoylation to promote breast cancer cell migration and sphere formation." (PMID 29955155, 2018). "By deacetylating SMAD4, SIRT1 represses the effect of TGF-β signaling on MMP7 (a SMAD4 target gene) and consequently cell migration and tumor metastasis in breast cancer and oral squamous cell carcinoma." (PMID 30250020, 2018). "The formation of TGF-β-SMAD4-IL-8 axis in breast cancer cells shows a synergistic regulation of multiple cytokines in chemotherapeutic resistance of breast cancer." (PMID 30175384, 2018). "Here the authors report the role of SIRT7 in inhibiting SMAD4-mediated breast cancer metastasis providing a possible therapeutic avenue." (PMID 28827661, 2017). "Snail1 has previously been reported to interact with the R-Smad, Smad3 and co-Smad, Smad4 to drive EMT in breast carcinomas." (PMID 29228645, 2017). "Current research shows that SMAD4 plays a key role in both tumor suppression and progression of breast cancer cells." (PMID 29179495, 2017). "We also found resveratrol activates SIRT7 deacetylase activity toward SMAD4 to inhibit breast cancer lung metastasis." (PMID 28827661, 2017). "Together, the data suggest SIRT7 against SMAD4 stability as a potential therapeutic target for lung metastasis and beneficial effects of resveratrol in breast cancer treatment." (PMID 28827661, 2017). "Further, protein levels of SIRT7 and SMAD4 were examined in a human breast cancer tissue array by immunohistochemistry microscopy." (PMID 28827661, 2017). "Compared with mock-treated cells, SMAD4 protein level was significantly increased in various breast cancer cells with SIRT7 KD." (PMID 28827661, 2017). "GATA3 abrogates Smad4 -mediated fascin overexpression, invadopodium formation, and invasion of breast cancer cells by abolishing the interaction between Smad4 and its DNA binding elements." (PMID 29285273, 2017). "A previous study showed that Cbl-b directly binded to Smad3 through a proline-rich motif, thereby preventing Smad3 from interacting with Smad4 and blocking nuclear translocation of Smad3 in breast cancer cells." (PMID 27494897, 2016).
breast carcinoma (continued). "Results of a study evaluating the role of TIF-1γ and its interaction with TGFβ1/SMAD4 signaling pathway as a prognostic factor in operable breast cancer have been published recently." (PMID 27561848, 2016). "There is a crosstalk between the TIF1γ and the TGFβ1/SMAD4 signaling that deteriorates the outcome of operable breast cancer patients and when combined together they can serve as an effective prognostic tool for those patients." (PMID 26040677, 2015). "Our present work clearly concludes that there is a crosstalk between the TIF1γ and the TGFβ1/SMAD4 pathway that can predict poorer outcome in operable breast cancer patients." (PMID 26040677, 2015). "Linoleic acid does not only induce PAI-1 (a prognostic marker for breast cancer) secretion through SMAD4 (similar to mothers against decapentaplegic-4) but also enhances the migratory potential of the highly invasive MDA-MA-468 breast cancer cell line." (PMID 24787299, 2014). "It has been reported that NAG-1-induced growth inhibition is abolished in TGF-β receptor type I mutant R1B/L17 cells, TGF-β receptor type II mutant RKO colon carcinoma cells, and Smad4 null MDA-MB468 breast cancer cells." (PMID 24759784, 2014). "One recent study also suggested that SMAD4 is required for TGF-β-induced EMT to mediate bone metastasis of breast cancer cells." (PMID 24625091, 2014). "Recent data demonstrated that blocking TGFβ signaling with a dominant-negative form of TGFβRI or Smad4 knockdown in human breast cancer cell lines decreased the ability of these cells to generate lung metastases when implanted as mammary tumors in mice." (PMID 24658161, 2014). "Two candidate genes that are of potential interest in clinical genetics of breast cancer are SMAD3 and SMAD4, encoding the key signaling transduction proteins of the Transforming Growth Factor-β (TGF-β) pathway." (PMID 21835029, 2011). "This study has demonstrated that expression levels of SMAD3 and SMAD4 are important factors in breast cancer but have different consequences." (PMID 21835029, 2011). "Several studies have demonstrated that tumor cell autonomous genetic inactivation of the TGF-β signaling pathway by knock-down of TGFBR2 or SMAD4 reduced the ability of MDA-MB-231 human basal-like breast cancer cells to metastasize to bone." (PMID 20504320, 2010). "An alteration of the SMAD4/DPC4 gene sequence was identified in one of eight breast carcinomas and one of eight ovarian carcinomas." (PMID 20565773, 2010). "Taken together, these results show that loss of BRCA1 or reduced BRCA1 expression significantly modulated TGF-β induced activation of Smad3 and Smad4 in breast cancer cells." (PMID 19768112, 2009). "The fact that aberrant expression of Smad4 is only seen some of ERα-positive infiltrating breast cancer is consistent with the heterogeneity of human breast carcinoma in biological features, development and progression, and therapy response." (PMID 19943940, 2009). "Significant reduced expression of Smad4 protein was found in some human carcinoma including breast cancer." (PMID 19943940, 2009). "Either overexpression of Smad3 or inhibition of Smad4 expression switches TGF-β to an activator for ERα transactivation in breast cancer cells." (PMID 19943940, 2009). "Further, WT-BRCA1, but not mutated BRCA1 increased the expression of Smad3 protein in a dose-dependent manner, while silencing of WT-BRCA1 by siRNA decreased Smad3 and Smad4 interaction induced by TGF-β in MCF-7 breast cancer cells." (PMID 19768112, 2009). "MCF-7 breast cancer cells were co-transfected with expression plasmids of Smad2, Smad3, Smad4, or Smad4 in combination with either Smad2 or Smad3." (PMID 19943940, 2009). "A complex of Smad3/4 mediates TGF-β inhibition of ERα-mediated estrogenic activity of gene transcription in breast cancer cells, and Smad4 is essential and sufficient for such repression." (PMID 19943940, 2009).